ADAM9 (ADAM metallopeptidase domain 9)
Diseases named in the same sentence as ADAM9 in open-access papers (continued):
Sharing a sentence is not in itself a finding about the gene and the disease.
endometrial cancer (3 papers, 2014 to 2020). Primary or metastatic malignant neoplasm involving the endometrium (mucous membrane that lines the endometrial cavity). "We evaluated the association between serum RCAS1 concentration and RCAS1/ADAM9 expression in 47 cervical and 48 endometrial cancer patients." (PMID 25177692, 2014). "On the other hand, this is the first report concerning ADAM9 expression in endometrial cancer wherein ADAM9 positivity was seen in 87% of cases (42 out of 48 cases) and ADAM9 expression was strong (3+) in 19 of 48 cases." (PMID 25177692, 2014). "On the other hand, prominent staining for ADAM9 was detected in cervical and endometrial cancer." (PMID 25177692, 2014). "For cervical and endometrial cancer in which RCAS1 is a clinical prognostic factor, tissue sampling and expression analysis of RCAS1 and ADAM9 can be easily performed." (PMID 25177692, 2014). "In 48 patients with endometrial cancer, 16, 14, 12, and 6 cases showed no expression, 1+, 2+, and 3+, respectively, for RCAS1, while for ADAM9, 6, 9, 14, and 19 cases had no expression, 1+, 2+, and 3+, respectively." (PMID 25177692, 2014).
metastatic tumors (3 papers, 2012 to 2021). "Although only one distant metastatic tumor was found in each mouse, the tumor incidence was 63% (5 of 8) in the control group, markedly higher than 11% (1 of 9) in the ADAM9 knockdown group." (PMID 34671207, 2021). "They found that ADAM8 was expressed significantly higher in metastatic tumors as well as identifying several proteinases of the ADAM-family (ADAM9, ADAM17, ADAM28, ADAMTS1, ADAMTS8 and ADAMTS15) -including ADAM8- which are HNSCC associated." (PMID 22369429, 2012). "In the control group, in which mice were injected with the control CE146T cells, all mice (100%) developed several distal metastatic tumors within 64 days after cancer cell injection, whereas only one mouse (20%) had one small distal metastatic tumor in the ADAM9 knockdown group." (PMID 34671207, 2021).
Obesity (3 papers, 2014 to 2021). Accumulation of substantial excess body fat. "To test transcriptional effects of miR-125a down-regulation in human obesity, we quantified the expression of its target genes Tef, Masp1, Rtn2, Ube2l3 and Adam9 in subcutaneous adipose tissue samples of obese patients." (PMID 24675842, 2014). "Regarding obesity, previous transcriptomics analyses have demonstrated how Adam9 is significantly up-regulated in obese AT and how it plays a major mediating role in a chain of interactions that connect local inflammatory phenomena to the alteration of AT metabolic functions." (PMID 32275707, 2020). "In early obesity, inflammatory cues in CCs were mediated by the upregulation of genes involved in cellular response to stress as DEAD-box helicase 5 (Ddx5), hypoxia inducible factor 1 subunit alpha (Hif1a), and ADAM metallopeptidase domain 9 (Adam9)." (PMID 34805147, 2021).
renal carcinoma (3 papers, 2008 to 2022). A carcinoma arising from the epithelium of the renal parenchyma or the renal pelvis. "Higher ADAM9 expression in renal cancer was significantly associated with shortened survival times (p = 0.026)." (PMID 18582378, 2008). "In accord with those reports, ADAM9 was strongly expressed in 7 of the 8 NCI-60 renal cancer cell lines." (PMID 22570691, 2012). "ADAM9 was significantly up-regulated in renal cancer in comparison to the adjacent normal tissue on mRNA level." (PMID 18582378, 2008). "In bivariate Spearman's rank correlations the ADAM9 protein expression in renal cancer correlated with the tumour grade, patient age and positive tumour resection status (R1)." (PMID 18582378, 2008). "Among the most altered genes, it has been shown that renal cancer progression can be promoted by upregulation of CXCL8, ADAM9, NDRG1, SOD2, SREBF1 and SREBF2 genes." (PMID 35505422, 2022).
Sepsis (3 papers, 2024 to 2025). Sepsis is defined as life-threatening organ dysfunction caused by a dysregulated host response to infection. "In contrast, ADAM9 suppresses efferocytosis and inhibits polarization toward an anti-inflammatory M2 phenotype in the context of sepsis-induced acute lung injury." (PMID 41181101, 2025). "The Venn diagram shows that a total of eight overlapping genes were discovered between ACSL4 co-expression genes and sepsis, including GK, CLEC4E, ACSL1, TGFBR3, ADAM9, AZI2, BCAT1, and CYP1B1." (PMID 39262873, 2024). "This suggests that ADAM9 may exert synergistic effects with TLR-mediated immune activation, collectively regulating the immune process in pediatric sepsis." (PMID 41305715, 2025).
emphysema (2 papers, 2022 to 2025). "Moreover, Macro_SPP1 cells showed elevated expression of protease genes (e.g., ADAM9, CTSL, CTSS, and MMP9) in COPD, which were associated with emphysema and airway remodeling." (PMID 40589761, 2025). "Moreover, ADAM9 has emerged as a key player in the pathogenesis of COPD/emphysema." (PMID 36522710, 2022). "The metalloprotease ADAM9 has been recently recognized as an important mediator of not only acute lung injury, but also COPD, being implicated in lung inflammation, alveolar septal apoptosis, emphysema, small airway fibrosis, and mucous cell metaplasia in mice." (PMID 36522710, 2022).
injury (2 papers, 2022 to 2025). Damage inflicted on the body as the direct or indirect result of an external force, with or without disruption of structural continuity. "Because ALD is similar to CCL4-induced chemical liver injury, this study was conducted to further explore the role of ADAM9 in the process of alcohol-induced liver injury." (PMID 35707386, 2022). "It was further demonstrated that the knockout of the ADAM9 gene could promote hepatocyte proliferation in alcohol-induced acute liver injury; i.e., the knockout of the ADAM9 gene can alleviate alcohol-induced acute liver injury." (PMID 35707386, 2022).
metabolic syndrome (2 papers, 2014 to 2025). A cluster of metabolic risk factors for CARDIOVASCULAR DISEASES and TYPE 2 DIABETES MELLITUS. "In this study, we investigated the potential link between ADAM9 variants and metabolic syndrome traits in a cohort of adult participants from Kuwait." (PMID 40330740, 2025). "Adam9 is an insulin-like growth factor binding protein-5 protease associated with adiponectin, which may modulate the development of the metabolic syndrome." (PMID 24675842, 2014). "For example, upregulated expression of Masp1 in obese patients could reflect adipose tissue inflammation, whereas Adam9 overexpression may underlie protective mechanisms against the metabolic syndrome." (PMID 24675842, 2014). "However, its role in the pathophysiology of metabolic syndrome remains unclear, and studies exploring the association between ADAM9 polymorphisms and metabolic traits are limited." (PMID 40330740, 2025).
myeloma (2 papers, 2016 to 2018). "ADAM9 can also function as an adhesion molecule by interacting with an αvβ5 integrin on myeloma cells." (PMID 27571068, 2016). "ADAM-9 also regulates myeloma cell induced ionterleukin-6 production by binding to αvβ5 integrin." (PMID 29393911, 2018). "ADAM-9 in human myeloma cells was further demonstrated to facilitate adhesion by binding to αvβ5 integrin, while the lymphoblastoid cells which do not express αvβ5 does not bind to ADAM-9." (PMID 29393911, 2018).
myocarditis (2 papers, 2019 to 2024). Myocarditis is a condition that is characterized by inflammation of the heart muscle (myocardium). "To investigate the role of ADAM9 in picornavirus infection in vivo, we used Adam9 KO mice and an infection model of EMCV-induced myocarditis." (PMID 38755212, 2024). "In the present study, we investigated the role of ADAM9 in picornavirus infection using Adam9 KO mice and an infection model of EMCV-induced myocarditis." (PMID 38755212, 2024). "Adam9 KO mice demonstrated unexpected sensitivity to EMCV infection and were also prone to developing fulminant myocarditis resulting in early mortality as compared to infected WT controls." (PMID 38755212, 2024). "Therefore, future studies will reveal whether the animals are now refractory to infection and uncover the role of ADAM9 in EMCV pathogenesis, including myocarditis." (PMID 30914507, 2019).
oral cancer (2 papers, 2019 to 2024). "Our research group has previously reported ADAM9 overexpression in oral cancer, and this study further explored its clinicopathological significance." (PMID 39441449, 2024). "Western blot and immunofluorescence results indicated that ADAM9, cathepsin V and kallikrein 5 were expressed at high levels in oral cancer cell lines." (PMID 30602733, 2019). "Consistently, among several salivary proteases, elevated ADAM9 levels are indeed considered a biomarker for OSCC screening and diagnosis, whereas an up-regulation of t-PA expression is not obviously found in oral cancer cells in comparison with adjacent non-malignant epithelial cells." (PMID 39441449, 2024).
osteosarcoma (2 papers, 2010 to 2022). A usually aggressive malignant bone-forming mesenchymal neoplasm, predominantly affecting adolescents and young adults. "By contrast, ASMTL-AS1 exacerbates osteosarcoma progression through the upmodulation of ADAM metallopeptidase domain 9 (ADAM9) expression." (PMID 35055115, 2022).
papillary carcinoma (2 papers, 2008 to 2015). A malignant epithelial neoplasm characterized by a papillary growth pattern. "This is in line with a high expression of ADAM9 in clear cell and papillary carcinomas, which are thought to originate from that region." (PMID 18582378, 2008). "We next analyzed whether there was an association between miR-126-3p expression and ADAM9 and SLC7A5 mRNA expression in the TCGA papillary thyroid cancer dataset, and found a significant inverse association with SLC7A5 mRNA expression (r = −0.257, p<0.01) but not with ADAM9 mRNA expression." (PMID 26244545, 2015).
prostate tumor (2 papers, 2013 to 2023). "In conclusion, our study demonstrated that the ADAM9/WISP-1 axis triggers primary prostate tumor growth and distant metastasis by cooperating with OBs in bone." (PMID 36778124, 2023).
retinal degeneration (2 papers, 2009 to 2016). Degeneration of the retina. "In summary, we have demonstrated a pathology localized to the POS-RPE junction and leading to retinal degeneration in Adam9−/− mice and shown that ADAM9 mutations cause retinal degeneration in human patients." (PMID 19409519, 2009). "Our data therefore uncover a physiological role for ADAM9, reveal what we believe may be a novel causative pathway for human retinal degeneration, and highlight a potentially overlooked pathological feature of retinal degenerations, including CRD and AMD." (PMID 19409519, 2009). "Interestingly, retinal degeneration in adulthood was also detected in the ADAM-9-deficient mouse." (PMID 27120619, 2016). "Unexpectedly, ADAM-9-deficient mice show no obvious developmental phenotype, but in adulthood, 20 months after birth, mice display retinal degeneration." (PMID 27120619, 2016).
squamous cell carcinoma (2 papers, 2019 to 2021). A carcinoma arising from squamous epithelial cells. "The expression of ADAM9 increased in accordance with cell malignancy malignant (i.e. staining was stronger in squamous cell carcinomas than in normal cervical cells)." (PMID 31030477, 2019). "In the present study, 52 (72.2%) squamous cell carcinoma, 18 (25.0%) adenocarcinoma and 2 (2.8%) adenosquamous cell carcinoma samples were positive for ADAM9 immunostaining." (PMID 31030477, 2019). "Thus, the prevalence of ADAM9 expression appears to be high in aggressive types of tumour (i.e. squamous cell carcinomas)." (PMID 31030477, 2019). "According to the final model obtained after employing the backward selection procedure, the odds of ADAM9-positive expression were 7.39 times more likely in patients with squamous cell carcinomas versus those patients with adenocarcinomas (95% CI 1.42, 38.51; p = 0.017)." (PMID 31030477, 2019). "Furthermore, ADAM9 expression was found in cases of cervical intra-epithelial carcinomas and in the squamous cell carcinomas." (PMID 31030477, 2019).
Vestibular schwannoma (2 papers, 2020 to 2021). A vestibular schwannoma (also known as acoustic neuroma, acoustic neurinoma, or acoustic neurilemoma) is a benign, usually slow-growing tumor that develops from the VIIIth cranial nerve supplying the inner ear. "Recently, we described a disintegrin and metalloproteinase 9 (ADAM9) overexpression by Schwann cells of vestibular schwannoma (VS) and suggested that it might be a marker for VS tumor growth and invasiveness." (PMID 33176868, 2020).
abdominal aortic aneurysm (1 paper, 2020). Enlargement and ballooning of the vessel that supplies arterial blood to the abdomen, pelvis and legs. "With evidence showing that other ADAMs (ADAM10 and ADAM17) play roles in the development of abdominal aortic aneurysm, a recent study demonstrated that ADAM9 expression was up-regulated in a murine abdominal aortic aneurysm model." (PMID 33096780, 2020).
acinar cell carcinoma (1 paper, 2004). "A total of 59 infiltrating PDACs, 32 specimens from patients with chronic pancreatitis, 11 endocrine tumours and 24 acinar cell carcinomas were immunohistochemically analysed for ADAM9 expression." (PMID 14997207, 2004). "In conclusion, we have demonstrated that ADAM9 is overexpressed in PDACs but not in endocrine tumours or acinar cell carcinomas." (PMID 14997207, 2004). "Staining for ADAM9 was detected in 58 out of 59 (98.3%) PDACs and in two out of 24 (8.3%) acinar cell carcinomas, but not in endocrine tumours." (PMID 14997207, 2004).
adenosquamous cell carcinoma (1 paper, 2019). "As shown by the results of the present study, ADAM9 was expressed in both adenocarcinomas and adenosquamous cell carcinomas." (PMID 31030477, 2019).
atopic dermatitis (1 paper, 2020). "To conclude, this study showed that the GCF concentrations of ADAM8, ADAM9, Cathepsin E, MMP8, CD10, Protein convertase 9, and uPA/Urokinase proteases were downregulated in moderate/severe atopic dermatitis patients compared to healthy controls." (PMID 33255937, 2020).
brain cancer (1 paper, 2023). A primary or metastatic malignant neoplasm affecting the brain. "Marked upregulation of ADAM9 in cancer cells and tissues is associated with several different cancers, such as lung, prostate, breast, and brain cancers." (PMID 36778124, 2023).
carcinoma in situ (1 paper, 2022). "Moreover, our GEO study found that the group with superficial transitional cell carcinoma with surrounding carcinoma in situ lesions, or the invasive carcinoma group had higher expression of ADAM9, further supporting the cell migration promoting the function of ADAM9." (PMID 35740916, 2022).
Childhood onset (1 paper, 2024). Onset of disease at the age of between 1 and 5 years. "To date, biallelic ADAM9 mutations have primarily been implicated in childhood-onset cone–rod dystrophy (CORD9), with the singular exception of an LCA subject harboring a homozygous truncating variant." (PMID 38892339, 2024).
chronic hepatitis C (1 paper, 2024). "In cohorts of individuals with chronic hepatitis C, elevated sMICA levels, functioned as the ADAM9 substrate, following viral clearance were associated with HCC progression as a means to evade NK-mediated immune surveillance." (PMID 39346916, 2024).
cone dystrophy (1 paper, 2018). An inherited ocular disorder characterized by the loss of cone cells, the photoreceptors responsible for both central and color vision. "No prior report of GUCY2D or ADAM9-related cone dystrophy involves broad macular involvement sparing the foveola." (PMID 30116628, 2018).
dilated cardiomyopathy (1 paper, 2024). Cardiomyopathy which is characterized by dilation and contractile dysfunction of the left and right ventricles. "In our study, post-mortem histology revealed that infected Adam9 KO mice develop a severe dilated cardiomyopathy along with increased viral proliferation compared to WT controls." (PMID 38755212, 2024). "Post-mortem cardiac histopathology demonstrated that Adam9 KO mice developed a severe dilated cardiomyopathy with increased interstitial edema between the myofibers, interrupting the tissue structure." (PMID 38755212, 2024).
esophageal tumor (1 paper, 2021). "IHC staining of ESCC specimens demonstrated that ADAM9 was more highly expressed in esophageal tumor cells, as compared to adjacent normal esophageal tissue." (PMID 34671207, 2021).
hilar cholangiocarcinoma (1 paper, 2018). A cholangiocarcinoma that arises from the junction, or adjacent to the junction, of the right and left hepatic ducts. "mRNA expression of ADAM-9, − 10, − 11, − 12, − 15, − 17, − 28, and − 33 was analyzed in human hilar cholangiocarcinoma (HC) samples." (PMID 29776401, 2018).
HIV-1 infection (1 paper, 2024). The type species of lentivirus and the etiologic agent of acquired immunodeficiency syndrome (AIDS). "To further address if HIV-1 infection resulted in a transient increase in ADAM expressions, we used RT-PCR to quantify ADAM9, 10 and 17 mRNA in infected and uninfected cells from both day 3 and 6 post infection." (PMID 38572241, 2024).
Hyperglycemia (1 paper, 2020). An increased concentration of glucose in the blood. "Knockdown of circ-ADAM9 inhibited the negative effect of hyperglycemia on the tubulogenic capacity of EPCs, whereas overexpression of circ-ADAM9 further weakened their tubulogenic capacity." (PMID 32661238, 2020).
Hypoglycemia (1 paper, 2021). A decreased concentration of glucose in the blood. "The mechanism increasing sNRP1 levels in obese T2D in response to hypoglycemia is unclear; however, post-hypoglycemic ADAM9 levels were also higher at similar timepoints as the elevated sNRP1 levels in T2D cases." (PMID 34248841, 2021). "Here, ADAM9 was increased at 4-hours post-hypoglycemia in T2D and at 24-hours post-hypoglycemia in both T2D and control subjects." (PMID 34248841, 2021). "Elevated ADAM9 levels were also observed 24h post-hypoglycemia both in control and T2D subjects." (PMID 34248841, 2021). "Interestingly, in T2D, ADAM9 levels increased sharply 4-hours post-hypoglycemia compared to either the 2h post-hypoglycemia timepoint (1356 ± 81 vs 1019 ± 68 RFU of ADAM9 4h post-hypo vs 2h post-hypo, p<0.01) or baseline (1356 ± 81 vs 1107 ± 60 RFU of ADAM9 4h post-hypo vs baseline, p<0.05)." (PMID 34248841, 2021). "Here we report the levels of soluble neuropilin-1 (sNRP1), NRP1 proteolytic enzyme ADAM9 and NRP1 ligands, VEGF and SEMA3A, in response to insulin-induced hypoglycemia in obese patients with T2D." (PMID 34248841, 2021). "However, 4-hours post-hypoglycemia, sNRP1, VEGF and ADAM9 were elevated in T2D(p<0.05)." (PMID 34248841, 2021).
leukopenia (1 paper, 2023). "Leukopenia is probably caused by paclitaxel released by ADAM9-dependent cap removal in the tumor microenvironment, which is subsequently secreted into the bloodstream or by paclitaxel released by circulating tumor-derived ADAM9." (PMID 37445886, 2023). "Together, these results indicate that our ADAM9-MSNs also release their cytotoxic contents in undesired cellular contexts, which suggests that the ADAM9-MSNs are most likely to not reduce neuropathy and leukopenia in a clinical setting." (PMID 37445886, 2023). "Therefore, we developed an optimized ADAM9-responsive MSN (OPT-MSN) and assessed the potential clinical applicability of these OPT-MSNs by addressing the potential cytotoxicity on key cell types involved in neurotoxicity and leukopenia, as well as their efficacy in a PDAC xenograft model." (PMID 37445886, 2023).
liver diseases (1 paper, 2022). "The ADAM9 gene plays a crucial role in the occurrence and development of various liver diseases, but its role in acute alcoholic liver injury remains ambiguous." (PMID 35707386, 2022).
metastatic cancer (1 paper, 2016). A carcinoma which has spread from the original site of growth to another anatomic site. "The elevated expression of Adam9 is observed in metastatic cancer cells with high motility." (PMID 27334934, 2016).